CEP55 (centrosomal protein 55)
Diseases named in the same sentence as CEP55 in open-access papers (continued):
Sharing a sentence is not in itself a finding about the gene and the disease.
neuroblastoma (3 papers, 2021 to 2023). Neuroblastoma (NB) is the most common solid, extracranial childhood tumor. "In the current study, genome‐wide differential gene expression analysis identifies CEP55 as one of the few genes markedly downregulated after DDX21 knockdown in neuroblastoma cells." (PMID 33497018, 2021). "Our data demonstrate that DDX21 and CEP55 are valid therapeutic targets for the treatment of MYCN‐amplified neuroblastoma." (PMID 33497018, 2021). "Taken together, these data indicate that DDX21 and CEP55 play important roles in maintaining neuroblastoma cell cytoskeletal stability and in driving cell proliferation." (PMID 33497018, 2021). "Here, we show that N‐Myc protein binds to the DDX21 gene promoter, leading to increased CEP55 expression, neuroblastoma cell cytoskeletal stability, and cell proliferation." (PMID 33497018, 2021). "Knocking down DDX21 or CEP55 significantly decreases neuroblastoma cell cytoskeletal stability and cell proliferation." (PMID 33497018, 2021). "The results therefore indicate that DDX21 regulates CEP55 expression and promotes neuroblastoma progression in vivo." (PMID 33497018, 2021). "In human neuroblastoma tumor tissues, high CEP55 gene expression correlated with high DDX21 gene expression and independently predicts poor patient survival." (PMID 33497018, 2021). "N‐Myc upregulated DDX21 gene transcription, which subsequently upregulated CEP55 transcriptional elongation and resulted in increased neuroblastoma cell proliferation in vitro and tumor progression in mice." (PMID 33497018, 2021). "Our data demonstrate that DDX21 and CEP55 are potential therapeutic targets for MYCN‐amplified neuroblastoma." (PMID 33497018, 2021). "Knocking down DDX21 or CEP55 reduced neuroblastoma cell cytoskeleton stability and cell proliferation and all but abolished clonogenic capacity." (PMID 33497018, 2021). "Genome‐wide differential gene expression studies identified centrosomal protein CEP55 as one of the genes most dramatically downregulated after DDX21 knockdown in MYCN‐amplified neuroblastoma cells." (PMID 33497018, 2021). "In summary, the results indicate that DDX21 and CEP55 are essential for neuroblastoma cell proliferation and survival." (PMID 33497018, 2021). "We then assessed whether DDX21 or CEP55 is required for neuroblastoma cell viability and/or proliferation." (PMID 33497018, 2021). "We therefore examined whether DDX21 or CEP55 plays key roles in microtubule stability in neuroblastoma cells." (PMID 33497018, 2021). "For instance, DDX21 was reported to induce CEP55 expression, MYCN-amplified neuroblastoma cell proliferation, and tumorigenesis." (PMID 35371306, 2022). "In human neuroblastoma tissues, a high level of DDX21 expression correlated with a high level of N‐Myc expression and with CEP55 expression, and independently predicted poor patient prognosis." (PMID 33497018, 2021). "Furthermore, a few studies have shown that CEP55 is involved in the proliferation process of kidney cancer cells, NSCLC cells, and neuroblastoma cells." (PMID 37274251, 2023). "Taken together, our data show that DDX21 induces CEP55 expression, MYCN‐amplified neuroblastoma cell proliferation, and tumorigenesis, and that DDX21 and CEP55 are valid therapeutic targets for the treatment of MYCN‐amplified neuroblastoma." (PMID 33497018, 2021). "In addition, high DDX21 expression correlated with high N‐Myc and centrosomal protein 55 (CEP55) expression and predicted poor patient prognosis in human neuroblastoma." (PMID 33497018, 2021). "In summary, these data demonstrate that N‐Myc regulates DDX21 expression and DDX21 regulates CEP55 expression in human neuroblastoma and that high DDX21 and high CEP55 expressions are independent prognostic markers of poor outcome in human neuroblastoma patients." (PMID 33497018, 2021).
pancreatic adenocarcinoma (3 papers, 2018 to 2025). "After the OS analysis of these 10 target genes, we found that 4 were OS-associated genes in pancreatic adenocarcinoma: ARHPAG32, HOXA10, CCND1 and CEP55." (PMID 29769534, 2018).
adenoma (2 papers, 2020 to 2024). A neoplasm arising from the epithelium. "Our findings showed that CEP55 expression significantly increases as the tumor gains sequential mutations in CRC driver genes, a phenomenon driving adenoma to carcinoma progression of CRC." (PMID 38250876, 2024). "Interestingly, heterozygous Cep55wt/Tg mice developed a lower percentage of adenomas (~20%) and hyperplasia (~8%), suggesting that single copy overexpression of Cep55 is sufficient to initiate tumorigenesis, although the latency significantly differs between Cep55Tg/Tg and Cep55wt/Tg mice." (PMID 33087841, 2020).
ciliopathies (2 papers, 2021 to 2023). "Notably, truncating nonsense mutations in CEP55 are associated with MKS-like syndrome, a lethal fetal ciliopathy." (PMID 34710087, 2021).
colitis (2 papers, 2022 to 2024). Inflammation of the colon. "A PPI network based on DEGs was constructed using STRING, and a highly interconnected cluster was identified as a potential functional molecular complex of colitis, including 8 hub genes, that is, NDC80, PBK, CEP55, RRM2, ASPM, NCAPG, TOP2A, and CDKN." (PMID 38661103, 2024). "We also examined SGK1, CEP55, ACSL1, OLFM4, DPP10, and MGP expression in the colon tissues of dextran sodium sulfate‐induced colitis mice." (PMID 34939750, 2022). "To further confirm the differential expression of these candidate genes between ulcerative colitis and normal groups, we determined the mRNA expression of SGK1, CEP55, ACSL1, OLFM4, MGP, and DPP10 in colon tissues of DSS‐induced colitis mice." (PMID 34939750, 2022). "In addition, we also examined the expression of SGK1, CEP55, ACSL1, OLFM4, DPP10, and MGP in the colon tissues of dextran sulfate sodium‐induced colitis mice." (PMID 34939750, 2022). "In addition, we also examined the expression of SGK1, CEP55, ACSL1, OLFM4, DPP10, and MGP in the colon tissues of DSS‐induced colitis mice." (PMID 34939750, 2022).
diffuse large B-cell lymphoma (2 papers, 2023 to 2025). "The prevalence of CEP55 mutations was highest in uterine endometrial carcinoma (4.91%, 26/529), and then in diffuse large B-cell lymphoma (2.08%, 1/48)." (PMID 40723362, 2025).
gallbladder cancer (2 papers, 2023 to 2024). "Overall, the failure of mitosis in gallbladder cancer cells after knockdown of CEP55 causes severe DNA damage and even apoptosis, which in turn inhibits cell proliferation." (PMID 37274251, 2023). "It was worth noting that the mRNA levels of PLK1 and CEP55 were significantly upregulated in gallbladder cancer tissues than in adjacent tissues." (PMID 37274251, 2023). "Overall, we demonstrated that high expression of CEP55 promotes the proliferation of gallbladder cancer cells in vitro and in vivo." (PMID 37274251, 2023). "Overall, it was suggested that apoptosis occurs after silencing the expression of CEP55 in gallbladder cancer cells." (PMID 37274251, 2023). "Quantitative analysis showed that the proportion of multinucleation and nuclear fragmentation in gallbladder cancer cells increased after knocking down CEP55." (PMID 37274251, 2023). "Subsequently, based on gallbladder cancer tissue validation, we finally determined that CEP55 is a vital gene involved in the progression of gallbladder cancer." (PMID 37274251, 2023). "Here, we observed that gallbladder cancer cells after CEP55 knockout showed obvious tailing and appeared binucleate or even multinucleate, indicating the instability of the gallbladder cancer cell genome and DNA damage." (PMID 37274251, 2023). "Expectedly, subsequent Kaplan–Meier analysis and Cox regression analysis suggested that CEP55 was suitable as an independent predictor to help determine the prognosis of patients with gallbladder cancer." (PMID 37274251, 2023). "Our findings provide further insight into why CEP55 is a target for precision medicine therapy for gallbladder cancer." (PMID 37274251, 2023). "But the expression of CEP55 in gallbladder cancer and its role in the progression of gallbladder cancer remains to be elucidated." (PMID 37274251, 2023). "The relationship between the expression of CEP55 protein and clinical features in gallbladder carcinoma." (PMID 37274251, 2023). "Collectively, our studies led us to conclude that CEP55, highly expressed in gallbladder carcinoma, can be used as a potential independent predictor for disease diagnosis and prognostic prediction." (PMID 37274251, 2023). "Moreover, knockdown of CEP55 in gallbladder cancer cells ultimately affects the proliferative activity of the cells through AKT and ERK pathways mediated by cell cycle arrest, DNA damage, and even apoptosis." (PMID 37274251, 2023). "To further decipher the molecular signaling network involved in CEP55 accelerating the proliferation and survival of gallbladder cancer cells, we employed immunofluorescence assays to detect the effect of downregulation of CEP55 on AKT and ERK-dependent signaling pathways." (PMID 37274251, 2023). "Likewise, the protein expressions of CEP55 were obviously increased in 174 gallbladder cancer tissues." (PMID 37274251, 2023). "In combined analysis, CEP55 was markedly positively correlated with PLK1 in gallbladder cancer, R = 0.557, confirming that CEP55 may play a vital role in the progression of gallbladder cancer as PLK1." (PMID 37274251, 2023). "It has been reported that PLK1 is upregulated in gallbladder cancer and is associated with poor prognosis in gallbladder cancer patients, while the role of CEP55 in gallbladder cancer has not been reported." (PMID 37274251, 2023). "Meanwhile, the risk ratio of CEP55 overexpression was HR = 1.76 (CI: 1.22–2.55), revealing that CEP55 may be a promising predictor of the prognosis of patients with gallbladder cancer." (PMID 37274251, 2023). "Therefore, gallbladder cancer cells show DNA damage because of cell division failure after knocking down CEP55." (PMID 37274251, 2023).
gallbladder cancer (continued). "However, so far, it has remained unknown whether CEP55 is involved in the occurrence and development of GBC, and the role of the AKT and ERK signaling networks in the effect of CEP55 on gallbladder cancer remains to be elucidated." (PMID 37274251, 2023). "In addition, the results of western blot showed that the phosphorylation levels of AKT (Ser473), GSK-3 β (Ser9), and ERK1/2 (Thr202/Tyr204) decreased in gallbladder cancer cells after CEP55 knockdown, but the protein expression level of FOXO3a increased in the siCEP55 group." (PMID 37274251, 2023). "Consistent with previous studies, we found that the proliferation ability of gallbladder cancer cell lines NOZ and SGC-996 was obviously reversed after CEP55 knockdown." (PMID 37274251, 2023). "Correlation studies suggested that the expression of CEP55 in gallbladder cancer was significantly positively correlated with that of PLK1, indicating that CEP55 has potential as a molecular target for gallbladder cancer therapy like PLK1." (PMID 37274251, 2023). "Notably, it showed that the expression of CEP55 was positively correlated with TNM stage (X2 = 6.345, P = 0.012) and negatively correlated with the degree of differentiation of gallbladder carcinoma (X2 = 6.702, P = 0.010)." (PMID 37274251, 2023).
melanoma (2 papers, 2023 to 2025). A malignant, usually aggressive tumor composed of atypical, neoplastic melanocytes. "Greater thickness and advanced stage indicate poorer survival outcomes, so these findings indicate that high CEP55 expression is linked to a worse prognosis in patients with melanoma." (PMID 40918457, 2025). "In addition, elevated CEP55 expression was associated with improved responsiveness to immunotherapy in patients with melanoma, highlighting its potential as a critical biomarker for precision medicine approaches." (PMID 40918457, 2025). "Besides, CEP55 overexpression was associated with more favorable responses to immunotherapy in melanoma patients." (PMID 40918457, 2025). "This study identified CEP55 as a potential therapeutic target for melanoma, offering new insights into improving therapeutic responses and reducing drug resistance." (PMID 40918457, 2025). "Databases (GEPIA, Sangerbox, Kaplan-Meier plotter, and TIMER) were used to analyze the expression of CEP55 and its correlation with clinical data of melanoma patients." (PMID 40918457, 2025). "First, we analyzed the relationship between CEP55 and various immune cells in melanoma using the TIMER platform." (PMID 40918457, 2025). "Our investigation demonstrated that CEP55 facilitated melanoma progression by promoting cellular proliferation, migration, and invasion, both in vitro and in vivo." (PMID 40918457, 2025). "These complementary assays collectively established CEP55 as a critical regulator of melanoma proliferative capacity." (PMID 40918457, 2025). "IHC staining further confirmed this finding, showing that CEP55 expression was upregulated in melanoma." (PMID 40918457, 2025). "In future studies, we will aim to explore the molecular mechanisms through which CEP55 regulates melanoma." (PMID 40918457, 2025). "In 50 pairs of tumor and paratumor tissues, CEP55 RNA expression was markedly elevated in melanoma tissues." (PMID 40918457, 2025). "To investigate the functional role of CEP55 in melanoma, we silenced its expression in A375 and A2058 melanoma cell lines by transfecting with lentivirus-derived shRNAs (shCEP55-1 and shCEP55-2, respectively)." (PMID 40918457, 2025). "Despite these advances, the molecular mechanisms of CEP55 in melanoma remained poorly understood, necessitating further investigation." (PMID 40918457, 2025). "To further assess CEP55 expression in AM, we performed qRT-PCR and WB to quantify CEP55 levels in melanoma tissue samples and cell lines." (PMID 40918457, 2025). "To delineate CEP55’s transcriptomic regulatory network in melanoma progression, we conducted RNA-seq via the Illumina NovaSeq 6000 platform on A2058 shCEP55-1 and A2058 NC cells." (PMID 40918457, 2025). "CEP55 expression in melanoma tissues and cell lines was analyzed by RT-qPCR, Western blotting, and immunohistochemistry (IHC)." (PMID 40918457, 2025). "CCK-8 assays revealed that reducing CEP55 expression markedly suppressed melanoma cell proliferation." (PMID 40918457, 2025). "Building upon the clinical correlation between elevated CEP55 expression and melanoma progression in advanced M stage and increased Breslow thickness, we compared the migration and invasion capabilities of NC, shCEP55-1, and shCEP55-2 cells." (PMID 40918457, 2025). "Collectively, these findings demonstrated that CEP55 knockdown significantly impaired the migration and invasion abilities of melanoma cells in vitro." (PMID 40918457, 2025). "CEP55 overexpression is associated with Breslow thickness and TNM stage in melanoma tissues and cell lines." (PMID 40918457, 2025). "WB analysis also verified increased CEP55 expression in 6 melanoma cell lines compared to human primary melanocytes." (PMID 40918457, 2025). "Collectively, these results indicated that reducing CEP55 expression significantly diminished the proliferation capacity of melanoma cells." (PMID 40918457, 2025).
melanoma (continued). "As a key regulator of melanoma cell proliferation, invasion, and migration, CEP55 represents a potential therapeutic target." (PMID 40918457, 2025). "The PI3K/AKT signaling pathway, a downstream effector of CEP55, plays a pivotal role in melanoma pathogenesis, and CEP55 facilitates the progression of various tumors." (PMID 40918457, 2025). "Downregulation of CEP55 increased tumor sensitivity to BRAFi, highlighting its central role in the drug resistance of melanoma cells." (PMID 40918457, 2025). "Our findings from RNA-seq and western blot analyses confirmed that CEP55 drived melanoma progression by activating the downstream MAPK signaling pathway." (PMID 40918457, 2025). "Given the low response rate of this subtype to existing adjuvant treatment regimens, the abnormal expression of CEP55 may provide a new idea to reveal the progression mechanism in melanoma." (PMID 40918457, 2025). "Collectively, these findings indicated that high CEP55 expression may predict a favorable response to immunotherapy in patients with melanoma and serve as a potential biomarker for immunotherapy response." (PMID 40918457, 2025). "The increased expression of CEP55 in melanoma correlates with poor prognosis." (PMID 40918457, 2025). "CEP55 knockdown inhibited melanoma cell proliferation, migration, and invasion." (PMID 40918457, 2025). "Building upon our preliminary findings, future studies should include large-scale clinical trials involving patients with melanoma to evaluate whether CEP55 is a reliable predictor of response to immunotherapy." (PMID 40918457, 2025). "Notably, B cell-related signaling pathways were significantly enriched following CEP55 knockdown, indicating that CEP55 may influence the immune response in melanoma." (PMID 40918457, 2025). "In addition, melanoma cells exhibited increased sensitivity to BRAFi after the CEP55 knockdown." (PMID 40918457, 2025). "However, whether CEP55 influences BRAFi resistance in melanoma by modulating the MAPK pathway remains unclear." (PMID 40918457, 2025). "Additionally, the mitogen-activated protein kinase (MAPK) signaling pathway was significantly enriched, indicating that CEP55 may regulate this pathway to affect melanoma progression." (PMID 40918457, 2025). "Moreover, in the GSE91061 melanoma cohort treated with PD1 and CTLA4 inhibitors, CEP55 expression decreased considerably after ICI treatment in the CR/PR group." (PMID 37484531, 2023).
multiple myeloma (2 papers, 2022 to 2024). "Additionally, in multiple myeloma, CEP55 was implicated in the top 10 genes promoting drug resistance." (PMID 38250876, 2024).
psoriasis (2 papers, 2022 to 2025). An autoimmune condition characterized by red, well-delineated plaques with silvery scales that are usually on the extensor surfaces and scalp. "Although research on its role in CD is limited, CEP55 has been identified as a key gene associated with immune responses, cell cycle regulation, and the Wnt signaling pathway in psoriasis." (PMID 40406126, 2025). "In psoriasis, the five diagnostic hub genes (KIF4A, DLGAP5, NCAPG, CCNB1, and CEP55) were predominantly expressed in keratinocytes, with significantly higher expression levels in patient samples compared to controls." (PMID 40406126, 2025). "This integrative approach highlighted KIF4A, DLGAP5, NCAPG, CCNB1, and CEP55 as key shared biomarkers for both psoriasis and CD." (PMID 40406126, 2025). "In the psoriasis dataset (GSE13355), the AUC values for KIF4A (AUC = 0.99), DLGAP5 (AUC = 1), NCAPG (AUC = 0.99), CCNB1 (AUC = 0.99), and CEP55 (AUC = 0.99) exhibited exceptional diagnostic performance, with all values exceeding 0.7." (PMID 40406126, 2025). "In the psoriasis validation cohort (GSE14905), the AUC values for KIF4A, DLGAP5, NCAPG, CCNB1, and CEP55 were 0.96, 0.97, 0.96, 0.98, and 0.93, respectively." (PMID 40406126, 2025).
T cell lymphoma (2 papers, 2021 to 2025). "CEP55 overexpression has been implicated in T-cell lymphoma and genome instability." (PMID 33692779, 2021).
thyroid cancer (2 papers, 2021). "High expression of CEP55 can promote the proliferation of lung, breast and thyroid cancers." (PMID 33190424, 2021).